SNORA13 (small nucleolar RNA, H/ACA box 13)
Synonyms: ACA13
Gene: Small nucleolar RNA gene on chromosome 5 (112,161,485 to 112,161,617, forward strand). Ensembl gene ENSG00000238363.
Gene Ontology:
Biological process: RNA processing
Cellular component: nucleolus
Homologues: Orthologues: chimpanzee SNORA13 (98% identical), macaque SNORA13 (98% identical), pig SNORA13 (91% identical), guinea pig SNORA13 (90% identical), rat LOC120095734 (83% identical), rat LOC120098360 (83% identical), rat LOC120096787 (71% identical), mouse Gm54625 (43% identical).
Diseases named in the same sentence as SNORA13 in open-access papers:
SNORA13 is named in the same sentence as 5 diseases in open-access papers, as found by Europe PMC text mining. Sharing a sentence is not in itself a finding about the gene and the disease. The quoted sentences say what the papers report.
osteosarcoma (2 papers, 2020 to 2021). A usually aggressive malignant bone-forming mesenchymal neoplasm, predominantly affecting adolescents and young adults. "In vitro, SNORA13 induce resistance to Dox in human osteosarcoma, by modulating the expression of genes involved in DNA damaging sensing, DNA repair, ribosome biogenesis, and proliferation." (PMID 34552157, 2021). "This trend was not cell line-specific: indeed SNORD3A, SNORA13 and SNORA28 and their respective host genes were progressively up-regulated also in the Dox-resistant variants Saos-2/DX30, Saos-2/DX100 and Saos-2/DX580 derived from Dox-sensitive Saos-2 cells, a second human osteosarcoma cell line." (PMID 32599901, 2020).
colorectal cancer (1 paper, 2025). A primary or metastatic malignant neoplasm that affects the colon or rectum. "In addition, we have investigated the ectopic expression of SNORA13 in vitro, and our results showed that the SNORA13 overexpression promotes the clone formation in colorectal carcinoma cells." (PMID 40529507, 2025).
cancer (2 papers, 2025). A tumor composed of atypical neoplastic, often pleomorphic cells that invade other tissues. "Mechanistically, we performed transcriptomic (RNA-seq), translatomic (Ribo-seq), and proteomic analyses, which revealed that translation efficiency is markedly reduced upon SNORA13 knockdown, particularly in cancer cells." (PMID 40529507, 2025). "In summary, our data indicates that upregulation of SNORA13 in CRC and demonstrates its anti-cancer efficacy by suppressing SNORA13 using ASO." (PMID 40529507, 2025). "Moreover, data analysis using TCGA database suggested that the upregulation of SNORA13 is universal in various types of cancers." (PMID 40529507, 2025). "To study whether suppressing of SNORA13 exhibits synergistic effect with 5-FU administration, we introduced SNORA13 ASO and 5-FU respectively and combinatorically, and our data demonstrated SNORA13 ASO markedly enhances the anti-cancer efficacy of 5-FU." (PMID 40529507, 2025). "Consequently, the suppression of both the host gene EPB41L4A-AS1 and SNORA13 may yield a synergistic anti-cancer effect." (PMID 40529507, 2025). "Among these downregulated genes, we noticed that a well-known anti-cancer target, Nicotinamide N-methyltransferase (NNMT), is significantly downregulated upon SNORA13 knockdown." (PMID 40529507, 2025). "Next, the xenografted tumor model in nude mice demonstrated that the smaller tumorigenesis in SNORA13 knockout HT29 cell lines, and SNORA13 ASO enhances the anti-cancer efficacy of 5-FU." (PMID 40529507, 2025). "Importantly, our attempts using combinatorial administration of SNORA13 ASO and 5-FU showed a superior anti-cancer effect compared to 5-FU administration only, suggesting a potential novel therapeutical approach." (PMID 40529507, 2025).
tumor (2 papers, 2020 to 2025). "Next, xenografted tumor model in nude mice was established and our data demonstrated the smaller tumorigenesis in SNORA13 knockout HT29 cell lines." (PMID 40529507, 2025). "In this study, our data revealed SNORA13 is highly expressed in CRC tumor tissues compared to adjacent normal tissues." (PMID 40529507, 2025). "Both results suggested that losing SNORA13 suppresses cell proliferation in cultured CRC cell lines and tumor growth in xenograft tumor models." (PMID 40529507, 2025). "Together, our data suggested administration of knockdown of SNORA13 suppresses CRC proliferation and tumor growth via repressing protein synthesis and inhibiting NNMT level." (PMID 40529507, 2025).
SNORA13 also shares sentences with these, for which no sentence is quoted: colon adenocarcinoma (1 paper).